FAP (fibroblast activation protein alpha)
Diseases named in the same sentence as FAP in open-access papers (continued):
Sharing a sentence is not in itself a finding about the gene and the disease.
tumor (continued). "Since the flow cytometry panel used to categorize these FAP+CD45+ cells consisted of only macrophage markers, those data do not exclude the possibility that some of the FAP+CD45+ tumor cells were NK cells." (PMID 38196606, 2023). "It has been detected that fibroblast activation protein (FAP) expression which acts as a surrogate marker for CAFs was significantly higher in HG T1 tumours that progress to MIBC than in tumours that non-progress." (PMID 36928373, 2023). "Furthermore, the CAF maturation qualified by the expressions of fibroblast activation protein (FAP) and α-smooth muscle actin (SMA) has a significant impact on tumor growth and progression." (PMID 38017374, 2023). "Further studies are required to verify if FAP cell-surface expression is limited to the murine stroma, or if the initially FAP-surface low expressing (U87MG) or negative tumor cells (PC3) turned out to be FAP-positive when exposed to murine CAFs." (PMID 37284857, 2023). "While the expression level of FAP is low to non-detectable in normal organs, it is greatly upregulated at sites of tissue remodeling and tumor stroma." (PMID 36831535, 2023). "It is to be noted however that, although not significant, FAP(hF1) UCAR T-cells alone did decrease tumor growth, compared to UT-cell group (p=0.051)." (PMID 37251405, 2023). "As in most tumor types, including in PDAC,FAP is expressed on cells in the stroma, we do not expect FAP tPDT to directly kill the tumor cells." (PMID 37485886, 2023). "Infiltrating FAP-CAR T cells, although highly motile, initially accumulated within the stromal cell and collagen-rich regions surrounding tumor nests being restricted in their mobility by the stroma and prevented from entering tumor nests." (PMID 37607999, 2023). "FAP-inhibitor radiopharmaceuticals have been designed for PET/CT imaging, demonstrating a favorable biodistribution in normal tissues, a high tumor-to-background ratio, and high efficacy of [68Ga]FAPI PET/CT in staging and restaging tumors eligible for neo-adjuvant treatment and surgery." (PMID 37892020, 2023). "The genes encoding the fibroblast activation protein (FAP) and the connective tissue growth factor (CTGF) can function in tumor-associated stromal cells but are practically inactive in normal adult cells." (PMID 37108352, 2023). "Activated CAFs produce FAP, TGF-β and platelet-derived growth factor (PDGF), favouring tumour cell growth and invasion, extracellular matrix deposition, and angiogenesis within the tumour matrix." (PMID 36284271, 2022). "In most tumors, FAP is not expressed on tumor cells, and in these cases, consideration of clustering impacts the choice of radionuclide used." (PMID 36178531, 2022). "These patients with high tumor mRNA FAP expression had a more aggressive clinical course and significantly shorter survival (12 months) compared to those without altered FAP expression (28 months, log-rank p = 0.016)." (PMID 35052475, 2022). "Therefore, FAP inhibitors (FAPis) have recently been developed for PET imaging and radioligand therapy, exploring the clinical application in different tumor sub-types." (PMID 35327325, 2022). "In murine tumour models the probe had a higher signal in FAP expressing tumours, but the study did not demonstrate selectivity over PREP." (PMID 35359378, 2022). "IHC results validated that the protein expression of FAP, BMP1, WNT5A were upregulated in tumor." (PMID 35999201, 2022). "QUESTION: Is FAPi PET imaging a reliable biomarker of FAP expression in cancer and tumor-adjacent non-cancer tissues?" (PMID 34740953, 2022). "However, it is clear that some CMS1 tumours, like CMS4 tumours, contain a considerable proportion of FAP + myofibroblasts." (PMID 35296803, 2022). "High FAP expression was detected in both primary and metastatic samples and was independent of tumor grade." (PMID 35608703, 2022).
tumor (continued). "Patients with both high FAP+ fibroblasts and SPP1+ macrophages exhibited the shortest PFS compared with the signature combination groups, suggesting that these two cell types can synergistically promote tumor progression." (PMID 35365629, 2022). "Upon response to overexpressed FAP-α on CAFs, the nanoassemblies disassociated into individual CDs to release LOS for reducing intratumoral stromal collagen production, resulting in ECM modulation and tumor hypoxia mitigation." (PMID 35875197, 2022). "[68Ga]Ga-FAPI-46 is a novel positron emission tomography (PET) ligand that targets fibroblast activation protein (FAP) expression as FAP inhibitor (FAPI) and could already show promising results in several tumor entities." (PMID 35325283, 2022). "On-tissue quantitative analyses of 215 surgically resected PDACs have shown that the mean occupancy rate of collagen in tumor tissues was 38.4%, while that of fibroblastic cell populations expressing ACTA2 and/or FAP was 33.3% (unpublished data related to our previous analyses)." (PMID 35805064, 2022). "The expansion of fibroblasts is seen in the early tumour stage where CAFs act as “tumour suppressors”, producing gap junctions which subsequently turn CAFs into “tumour promoters”, as activated by tumour-secreted factors such as PDGF, FAP, interleukin-4, interleukin-6 and prostaglandin E (PGE)." (PMID 36101394, 2022). "In addition, β-carotene was found to inhibit M2 macrophage polarization and fibroblast function via α-SMA, FAP, and TGF-β1; both types of cells modulate the behaviour of cancer cells in the tumour microenvironment." (PMID 35276890, 2022). "The FAP immunohistochemistry score correlated positively both with 68Ga-FAPi-46 SUVmax across cancer and tumor-adjacent non-cancer tissues (r = 0.781 [95% CI, 0.376–0.936], P < 0.001) and with SUVmean (r = 0.783 [95% CI, 0.379–0.936], P < 0.001)." (PMID 34740953, 2022). "Previous studies have also suggested that FAP-dominant fibroblasts likely contribute to the spatial exclusion of CD8 T cells within PDAC tumor beds, regardless of baseline levels of CD8+ cell infiltration." (PMID 35805064, 2022). "Among them, FAP has 50% amino acid sequence homology and 70% homology of catalytic structural domain with DPP4, and they can form heterodimerization complexes to synergistically regulate the growth, differentiation, adhesion, and metastasis of tumor cells." (PMID 35692767, 2022). "Quantification of the VAP-1-positive tumor area showed that FAP-IL2v treatment did not affect the expression of VAP-1-positive blood vessels." (PMID 35874707, 2022). "Immunohistochemical assays were performed to corroborate FAP and PSMA tumor expression." (PMID 36500804, 2022). "Taken together, our preliminary results support the notion that in patients treated with FAP-directed “cold” and “hot” therapies, the doses in the majority of normal organs would remain similar, regardless of tumor load or intensity of uptake." (PMID 35681588, 2022). "They noted that mhFAP CAR-T cells were able to significantly reduce FAP+ stromal cells and tumor growth, with no toxicity or negative effects on wound healing." (PMID 35211124, 2022). "Results showed an increase in COL10A1 protein in tumor tissue, and in BGN and FAP proteins involved in collagen fibril assembly and matrix degradation, respectively, emphasizing that these hub genes could have a crucial function in gastric tumorigenesis." (PMID 35328635, 2022). "Similarly, adenoviral anti-FAP vaccines are able to selectively deplete CAFs by stimulating a CD8+ T cell response, leading to the inhibition of tumor growth and metastasis in several murine cancer models." (PMID 36010899, 2022). "Fibroblast activation protein (FAP) is a cell surface antigen of reactive tumor stromal fibroblasts found in epithelial cancers but not in normal tissues." (PMID 35223381, 2022).
tumor (continued). "Furthermore, FAP-targeted in combination with near-infrared photoimmunotherapy were shown to recover the sensitivity to chemotherapy in CAF-rich tumors and induce tumor regression." (PMID 36324128, 2022). "Likewise, fibroblast activation protein (FAP) was also targeted by CAR T-cells in animal models, which increased cytotoxic function by reducing the number of tumor fibroblasts." (PMID 35814023, 2022). "FAP+ CAFs are immunosuppressive with increased ECM alignment and stiffness, and this is hypothesized to be a major factor in the transition from a tumor-resistant to tumor-permissive microenvironment." (PMID 36010899, 2022). "The genes SLC6A6 and FAP, that are up-regulated in the High-stroma/CMS4 subtype, show in-silico interaction with miR-30b which is down-regulated in tumors and in the stroma versus the epithelia component of the tumor." (PMID 36358609, 2022). "Fibroblast activation protein (FAP) is expressed mainly in activated stromal fibroblasts, present in the tumor microenvironment of most human epithelial tumors, but not on the cell membrane of normal fibroblasts." (PMID 35456554, 2022). "Even when applying different thresholds for FAP-imaging (three-, five-, seven-, and tenfold increase of FAPI enhancement in the tumor as compared with normal tissue), other groups describe a good tumor-to-background ratio, especially in the cervical region, for [68 Ga]Ga-FAPI-46 PET/CT." (PMID 35771317, 2022). "Tumours expressing high FAP levels (top 25%, q1) consisted mostly of CMS4 tumours (n = 144; 72%)." (PMID 35296803, 2022). "In addition, most patients showed marked differences between FAP and [18F]FDG in terms of tumor uptake and background activity, in both cases favoring FAP-ligands." (PMID 35349039, 2022). "Similar findings were obtained when a FAP vaccine was employed to stimulate the immune system against CAF, enabling CD8+ infiltration coupled to a decrease in macrophage infiltration in different pre-clinical tumor models." (PMID 35892828, 2022). "To assess whether FAP could function as a potential target for molecular imaging of peritoneal metastases, we measured FAP mRNA and protein expression in a cohort of primary CRC tumours with paired peritoneal metastases." (PMID 35296803, 2022). "68Ga-FAPi-46 PET SUVmax and SUVmean was correlated with FAP immunohistochemistry score in cancer and tumor-adjacent non-cancer tissues for each patient." (PMID 34740953, 2022). "The FAP-specific radiotracers are not a perfect pan-tumor agent, but some of the properties that make them unique are their high avidity to a wide range of malignant tumors, low background activity, and favorable image contrast." (PMID 35280710, 2022). "Depletion of FAP+ cells improves the metabolism and functions of CD8+ T cells within tumours." (PMID 35158891, 2022). "For FAP-targeted radiotherapy, an emerging strategy is to directly modify the inhibitor structure to enhance tumor uptake and retention while keeping the accumulation in nontarget tissues unchanged or decreasing it." (PMID 34593598, 2022). "In addition, tumor uptake for [18F]AlF-PSMA-FAPI-01 and [18F]AlF-PSMA-FAPI-02 was higher than that for the corresponding monomers [18F]FAPI-42 and [18F]AlF-PSMA-BCH in FAP-positive A549-FAP and PSMA-positive 22Rv1 tumor xenografts." (PMID 35337180, 2022). "FAP-expressing stromal cells were detected in all CMS4 and all CMS1 tumours." (PMID 35296803, 2022). "As a therapeutic radiopharmaceutical, 177Lu-FAP-2286 showed similar biodistribution by SPECT/CT as the imaging agent 68Ga-FAP-2286, and likewise, it had significant tumor uptake and long retention that appeared to improve symptoms manifested by pain reduction in 3 patients with advanced disease." (PMID 35608703, 2022).
tumor (continued). "Hence, we hypothesized that a radioligand targeting FAP could be used for pretherapeutic estimation of FAP expression prior to local or systemic therapy in UC, which addresses the unmet need for appropriate pretherapeutic lymph node and distant metastases staging in this tumor entity." (PMID 35325283, 2022). "Furthermore, a 68Ga-radiolabeled FAP inhibitor ligand, 68Ga-FAPI, was shown to target tumor tissue in head and neck tumors with high signal-to-background ratio." (PMID 35223381, 2022). "In this interim analysis of a prospective exploratory imaging trial, 68Ga-FAPi-46 PET biodistribution correlated strongly with FAP expression in cancer and tumor-adjacent non-cancer tissues across multiple cancer types." (PMID 34740953, 2022). "We have established NIR-PIT targeting CAFs using FAP mAbs and have demonstrated its tumor-suppressive effect without toxicity." (PMID 36418422, 2022). "It is important to note that the relatively short tumor retention time of FAP inhibitors is not attributable to low ligand affinity." (PMID 35631416, 2022). "Importantly, incubation of PAMF with tumor-conditioned medium (TCM) for 48 h resulted in a significant, approximately two-fold increase in FAP expression compared to the untreated control." (PMID 36230765, 2022). "The PD/SQ-derived and FR/SQ tumor-derived CAFs expressed high levels of fibroblast mRNA markers (via QPCR analyses) αSMA, PDGFRα and FAP, but very little or no epithelial cell marker EPCAM." (PMID 35982950, 2022). "We found a remarkably higher proportion of CD163+ immune cells and FAP-positive fibroblasts in MRI true-positive tumor lesions compared with either MRI false-negative tumor lesions or benign tissue." (PMID 36874403, 2022). "However, it has proven difficult to increase tumor retention for effective TRT, and more knowledge on FAP behavior is needed to overcome this problem." (PMID 35788730, 2022). "An FAP+, platelet‐derived growth factor receptor (PDGFR)α+, PDGFRβ+, CD45−, EpCAM−, CD31− CAF population isolated from mouse lung and melanoma tumours inhibit T‐cell function via programmed death ligands 1 and 2 (PD‐L1 and PD‐L2), which bind to the programmed death 1 receptor (PD‐1) on T cells." (PMID 33152121, 2021). "FAP is involved in the promotion and development of tumor growth and is typically overexpressed in activated fibroblasts in the tumor stroma, whereas it is absent in most normal healthy tissues." (PMID 34201111, 2021). "Specific conditional depletion of FAP+ TAMs, using diphtheria toxin in a bone marrow chimera of a FAP/diphtheria toxin receptor (DTR) transgenic mouse, permitted immunological control of tumor growth." (PMID 33868304, 2021). "[225Ac]Ac-FAPI-4 injection showed significant tumour growth suppression in PANC-1 xenograft mice indicating that [64Cu]Cu-FAPI-4 and [225Ac]Ac-FAPI-4 could be used in theranostics for the treatment of FAP-expressing pancreatic cancer." (PMID 33806468, 2021). "FAP, a common CAF marker, was found to play a significant role in the propagation of CCRCC as it formed protein complexes with the urokinase plasminogen activator receptor (uPAR), promoting more aggressive tumor invasion." (PMID 33808627, 2021). "In the cases of four patients with cervical and two patients with endometrial cancer, the physiological uptake of the surrounding tissue did not impair the sensitivity for FAP-targeted PET/CT of these two tumor entities." (PMID 34830898, 2021). "Fibroblast Activation Protein-α (FAP) is a transmembrane protein, functioning as a serine protease and plays an important role in reactive fibroblasts, promoting angiogenesis and altering the extracellular matrix (ECM), which are crucial for tumor progression." (PMID 34885196, 2021). "To explore the anti-tumor effect of ProIFN, we first determined the expression levels of tumor-enriched enzymes such as MMP-2, MMP-9, MMP-11, MMP-14, fibroblast activation protein alpha (FAP), and urokinase plasminogen activator (uPA) in a variety of tumor lines." (PMID 34620867, 2021).
tumor (continued). "In contrast, FAP is nearly absent in normal adult tissues, rendering it a rather specific target for tumor imaging." (PMID 34050405, 2021). "A FAP monoclonal antibody conjugated to DM1, a cytotoxic drug tubulin-binding maytansinoid with antimitotic activity, called FAP5-DM1, inhibits tumor growth leading to complete regressions in lung, pancreas, head and neck in xenograft cancer models." (PMID 33572223, 2021). "Our results demonstrate the potential utility of activating CD8 cell infiltration in the tumor microenvironment of PDAC, inhibiting FAP and its mechanisms, and blockade of CD200, as well as the potential of each of these proteins in companion diagnostics tests for immunotherapy treatments." (PMID 34771664, 2021). "CAFs can promote tumor genesis, metastasis, and drug resistance by secreting the cytokines and extracellular matrix proteins such as α-smooth muscle actin (α-SMA) and fibroblast activator protein (FAP)." (PMID 34906155, 2021). "Moreover, our findings indicate that Wnt2B transfers directly from tumor cells to fibroblasts through exosomes, thereby upregulate the expression of α-SMA and FAP in vitro and in vivo, which is correlated with our initial clinical data." (PMID 33731705, 2021). "PSN38@TPL-nsa treatment suppressed the expression of FAP and α-SMA in tumor tissues." (PMID 34802453, 2021). "In addition to FAP+, FSP+ stromal cells within ovarian carcinomas secrete factors that promote tumour growth by enhancing microvascularisation, stromal networks and protumourigenic paracrine signals." (PMID 33152121, 2021). "In addition, carbonic anhydrase IX (CAIX)-directed CAR-T and fibroblast activation protein-α (FAP)-directed CAR-T treatment exhibit observable “on-target, off-tumor toxicity”." (PMID 34975912, 2021). "Moreover, the high expression of LOX in tumor stroma was observed in the same regions of the high expression of α-SMA and FAP." (PMID 34930321, 2021). "As shown in a representative manner for patient #6, PD-L1, EGFR and EpCAM were expressed to a lower degree or on subsets of tumor cells while FAP expression was absent." (PMID 34484225, 2021). "In cases where the fascin staining was negative in tumor cells, fascin, FAP, and α-SMA expression was also poor in CAFs." (PMID 34477172, 2021). "Immunoblot analysis detected FAP in lysates of B16-F10 tumours but not in those of cultured B16-F10 cells, suggesting that FAP-expressing CAFs are present in tumour stromal tissue." (PMID 33299131, 2021). "Importantly, compared to normal tissues, extremely high correlations were observed among AEBP1, BGN, POST, and FAP in COAD, suggesting that the STMERN specifically formed in tumor tissues." (PMID 34239578, 2021). "The tumours were analysed via flow cytometry for the simultaneous expression of six CAF markers: alpha smooth muscle actin (αSMA), fibroblast activation protein alpha (FAPα), platelet derived growth factor receptor alpha and beta (PDGFRα and PDGFRβ), CD26/DPP4 and podoplanin (PDPN)." (PMID 34016130, 2021). "A significant positive correlation was found between the expression of FAP, pSTAT3, and CCL2 in the tumor stroma in patients with intrahepatic cholangiosarcoma, a highly aggressive primary desmoplastic tumor associated with poor overall survival and a high probability of recurrence." (PMID 34771577, 2021). "Notably, CAF subtypes with a low expression of β1-integrin, FAP, and PDGF receptor (PDGFR)β were assigned to a luminal location and correlated with reduced tumor progressiveness." (PMID 33806802, 2021). "IHC staining of tumor specimens via gastroscopical biopsy was used to validate the infiltration of immunosuppressive cells in tumors and showed that the uptake of 68Ga-FAPI-04 positively correlated with FAP expression." (PMID 35155199, 2021). "FAP targeting leads to degradation of the ECM, interfering in regulatory signaling and subsequently disrupts the supportive biological functions of stromal CAFs on the tumor growth." (PMID 34681246, 2021).